RGS1 (regulator of G protein signaling 1)
Description:
Regulates G protein-coupled receptor signaling cascades, including signaling downstream of the N-formylpeptide chemoattractant receptors and leukotriene receptors. Inhibits B cell chemotaxis toward CXCL12 (By similarity). Inhibits signal transduction by increasing the GTPase activity of G protein alpha subunits thereby driving them into their inactive GDP-bound form.
Synonyms: 1R20; BL34; IER1; IR20; HEL-S-87
Tractability: Small molecule: a structure with a bound ligand is known. Antibody: UniProt places it where antibodies can reach, with high confidence; its Gene Ontology location is reachable by antibodies, with high confidence. PROTAC: ubiquitination databases record sites on it.
Gene: Protein-coding gene on chromosome 1 (192,575,763 to 192,580,024, forward strand). Ensembl gene ENSG00000090104.
Subcellular location: Cell membrane; Cytoplasm, cytosol
Pathways (Reactome):
Signal Transduction: G alpha (i) signalling events; G alpha (q) signalling events
Gene Ontology:
Molecular function: G-protein alpha-subunit binding; GTPase activator activity; calmodulin binding; GTPase activity
Biological process: G protein-coupled receptor signaling pathway; leukotriene signaling pathway; positive regulation of GTPase activity; signal transduction; adenylate cyclase-inhibiting G protein-coupled receptor signaling pathway; immune response; negative regulation of G protein-coupled receptor signaling pathway
Cellular component: cytoplasmic side of plasma membrane; cytosol; plasma membrane
Genetic constraint (gnomAD): Loss-of-function variants: 9 observed, 19.37 expected, observed/expected ratio (o/e) 0.46, 90% interval 0.28 to 0.81. The upper end of that interval is the gene's LOEUF score, 0.81, which puts it in group 3 of 6, group 1 being the genes least tolerant of losing a copy. Missense variants: 235 observed, 234.65 expected, observed/expected ratio (o/e) 1, 90% interval 0.9 to 1.12. Synonymous variants: 79 observed, 78.93 expected, observed/expected ratio (o/e) 1, 90% interval 0.83 to 1.21.
Homologues: Orthologues: chimpanzee RGS1 (100% identical), macaque RGS1 (97% identical), dog RGS1 (89% identical), rabbit RGS1 (89% identical), pig RGS1 (88% identical), guinea pig RGS1 (87% identical), mouse Rgs1 (87% identical), rat Rgs1 (71% identical), tropical clawed frog rgs1 (51% identical), zebrafish rgs1 (32% identical). Paralogues in human: RGS3 (43% identical), RGS21 (39% identical), RGS4 (38% identical), RGS16 (35% identical), RGS5 (35% identical), RGS8 (35% identical), RGS18 (35% identical), RGS2 (34% identical), RGS12 (33% identical), RGS13 (32% identical), RGS9 (31% identical), RGS11 (29% identical), and 11 more.
Diseases named in the same sentence as RGS1 in open-access papers:
RGS1 is named in the same sentence as 113 diseases in open-access papers, as found by Europe PMC text mining. Sharing a sentence is not in itself a finding about the gene and the disease. The quoted sentences say what the papers report.
melanoma (12 papers, 2011 to 2025). A malignant, usually aggressive tumor composed of atypical, neoplastic melanocytes. "RGS1 in 1q31.2 has been linked to multiple autoimmune diseases, including multiple sclerosis, as well as poor prognosis in melanoma and diffuse large B cell lymphoma mediated by inactivation of Akt/ERK." (PMID 33109261, 2020). "Like our results, RGS1 protein expression was significantly associated with unfavorable prognosis of the patients in DLBCL and in melanoma." (PMID 37437037, 2023). "RGS1 was shown to be a novel target for inflammatory diseases as Rheumatoid arthritis, melanoma and cervical cancer." (PMID 37437037, 2023). "RGS1 is significantly upregulated in a variety of solid tumours, including renal cell tumours, melanoma, ovarian cancer, and cervical cancer, among others." (PMID 37924113, 2023). "RGS1 promotes melanoma progression by regulating Gαs-mediated inactivation of AKT and ERK, and is a novel therapeutic target and prognostic marker for melanomas." (PMID 35879796, 2022). "In melanoma cells, RGS1 can also be regulated by lncRNA taurine upregulated 1 (TUG1)/miR-29c-3p to promote the proliferation and invasion and inhibit cell apoptosis." (PMID 35879796, 2022). "To evaluate whether the RGS1 construct used in our study retained functional activity, we assessed its effects on cell migration and downstream signaling pathways in melanoma cells." (PMID 40754247, 2025). "Previous studies have reported that RGS1 contributes to melanoma progression." (PMID 40754247, 2025). "It was demonstrated that in melanoma, RGS1 can regulate Gαs-mediated phosphorylation of AKT and ERK to promote melanoma development; however, interestingly, this regulation is not involved in the hydrolysis process of GTP in GPCRs, and it has a non-GAP function." (PMID 37924113, 2023). "In recent years, RGS1 has been mainly studied in tumors, especially in melanomas." (PMID 35879796, 2022). "RGS1 has also been reported as a prognostic marker in melanoma or spondylarthritis, indicating that there are roles for RGS1 in other disease conditions, even though in the schizophrenia subset its expression seems to be decreased rather than increased as in those other diseases." (PMID 31150013, 2019). "RGS1 was overexpressed in a gene expression-profiling study of melanoma." (PMID 25521548, 2014). "In the present study, RGS1 was highly expressed in tumor tissues and correlated with shorter overall survival, which also appeared in several previous studies, including multiple myeloma, melanoma, nonsmall cell lung cancer, gastric cancer, diffuse large B-cell lymphoma, and so on." (PMID 34956194, 2021). "Wound healing assays demonstrated that RGS1 significantly enhanced melanoma cell motility, and immunoblot analysis revealed increased phosphorylation of ERK and AKT following RGS1 expression." (PMID 40754247, 2025). "Increased expression of lnc-TUG1 in melanoma promoted tumor growth and metastasis by regulating the TUG1/miR-129-5p/AEG-1 and TUG1/miR-29c-3p/RGS1 ceRNA regulatory axis." (PMID 33194692, 2020). "Using such tissue proteomics approaches, several potential biomarkers have been identified from melanoma, such as actin-related protein 2/3 complex, subunit 2 (ARPC2), fibronectin 1 (FN1), and regulator of G protein signaling 1 (RGS1)." (PMID 29039819, 2017).
celiac disease (11 papers, 2011 to 2025). An autoimmune genetic disorder with an unknown pattern of inheritance that primarily affects the digestive tract. "Polymorphic variants in RGS1 have been linked to chronic inflammatory diseases such as celiac disease, multiple sclerosis, and type I diabetes." (PMID 33302351, 2020). "According to our results the minor G allele of rs2816316 (RGS1) confers risk for having multiple AIDs, whereas in previous reports it has been the major T allele that predisposes to T1D and celiac disease." (PMID 29182645, 2017). "The pathogenesis of celiac disease (CD) has been related to polymorphisms in the regulator of G-protein signaling 1 (RGS1) and interleukin-12 A (IL12A) genes, but the existing findings are inconsistent." (PMID 27043536, 2016). "Associations of RGS1 SNPs have also been observed in numerous T cell-mediated autoimmune diseases, including type 1 diabetes, celiac disease, and multiple sclerosis." (PMID 23382860, 2013). "Conversely, previous reports of an overlap in association between T1D and celiac disease were in regions encoding genes highly expressed in T lymphocytes (RGS1, PTPN2 and CTLA4 in celiac; PTPN2 and CTLA4 in T1D)." (PMID 21852963, 2011). "Importantly, coinciding with this group were two additional disease genes associated with wheat allergies and Celiac Disease, rgs1 and scp2a, which contained three markers within intronic regions." (PMID 31843804, 2020). "In addition, a growing number of large GWAS in humans have identified a link between polymorphic variants in Rgs1 and chronic inflammatory diseases including celiac disease, multiple sclerosis, and type I diabetes." (PMID 27804980, 2016). "Another study in children was able to evidence the increased risk (>90%) of developing celiac disease by the genotype of five candidate genes (SH2B3, RGS1, TAGAP, cREL, and LPP)." (PMID 32365683, 2020).
multiple sclerosis (11 papers, 2006 to 2025). A progressive autoimmune disorder affecting the central nervous system resulting in demyelination. "Interestingly, RGS1 has been recently shown to be associated with multiple sclerosis (MS) and type 1 diabetes (T1D), both of which are T cell-mediated diseases." (PMID 27043536, 2016). "Both RGS1 and RASGRP1 variants associated with systemic lupus erythematosus, Crohn’s disease, rheumatoid arthritis, multiple sclerosis, blood pressure, type 1 diabetes, type 2 diabetes, urinary metabolites and response to chemotherapy." (PMID 27804980, 2016). "In addition, RGS1 induction was observed in PBMCs obtained from IFN-β-treated multiple sclerosis patients suggesting a possible, as yet unexplored, involvement of G-protein regulation in disease treatment." (PMID 21274427, 2010). "Furthermore, information from RINGdb has shown both of RGS1 protein and its known binding partners, including Gα i1, Gα i2, Gα i3, Gα o1 and α-2A adrenergic receptor, are present in multiple sclerosis (MS) lesions, suggesting they may have a role in pathological conditions." (PMID 17173697, 2006). "RGS1 protein is the most abundant RGS protein in the microglia and is a key gene of the immunomodulatory response to neuroinflammation as well as a key target of different immunological and neurodegenerative diseases such as multiple sclerosis, inflammatory bowel and Parkinson’s disease." (PMID 32753750, 2020).
gastric cancer (10 papers, 2016 to 2025). A primary or metastatic malignant neoplasm involving the stomach. "linked elevated RGS1 in gastric cancer to reduced cell proliferation and apoptosis, and noted its role in TAM activation and macrophage polarization, suggesting it as a key therapeutic target." (PMID 39400959, 2024). "RGS1, a regulator of G protein signaling 1, expression has been reported to have a significant effect on the survival of stomach cancer, and is associated with the differentiation degree of tumor." (PMID 35677557, 2022). "Although a former study reported that high expression of RGS1 was associated with a low differentiation degree of gastric cancer, our study proved for the first time that RGS1 was correlated with expression of Ki67." (PMID 37529094, 2022). "High expression of RGS1, RGS2 and RGS3 in patients with gastric cancer has been shown to be associated with poor prognosis or poor tumor stage." (PMID 38693916, 2024). "Another study shows that the high expression of tumour RGS1 is correlated with shortened OS in gastric cancer patients." (PMID 38081176, 2023). "RGS1 serves as a prognostic marker for poor outcomes in multiple types of cancers, including myeloma, gastric cancer, and B cell lymphoma." (PMID 37488117, 2023). "We evaluated the proliferation, migration, and invasion of gastric cancer cells, and determined the expression of RGS1 in NCIN87-DR cells." (PMID 37529094, 2022). "The purpose of this study was to investigate the role of RGS1 in gastric cancer in vitro and in vivo." (PMID 37529094, 2022). "High expression of RGS1 and RGS3 is associated with poor prognosis in patients with gastric cancer." (PMID 38693916, 2024). "Overall, this study showed that RGS1 might be an antitumor target for the treatment of gastric cancer." (PMID 37529094, 2022). "Similarly, in gastric cancer, RGS1 knockdown has been reported to reduce cell migration and growth." (PMID 40754247, 2025). "Therefore, RGS1 served as an antitumor target for the gastric cancer treatment." (PMID 37529094, 2022). "Our results suggest that RGS1 and RGS2 are adverse prognostic factors in some gastric cancer cohorts." (PMID 38693916, 2024). "Unlike its established roles in esophageal and gastric cancers, there is limited evidence linking RGS1 to colon cancer progression." (PMID 40754247, 2025).
breast carcinoma (9 papers, 2016 to 2025). "RGS1, as a type of GTPase-activating protein, regulates T cell trafficking to tumors by attenuating chemokine-mediated signals and increased expression of RGS1 was associated with poorer survival of patients with breast cancer." (PMID 38280104, 2024). "Several groups have also reported the overexpression of RGS1 transcript in various cancer tissues including breast cancer, cholangiocarcinoma, oesophageal carcinoma, glioblastoma multiforme, lung adenocarcinoma, and stomach adenocarcinoma." (PMID 38514625, 2024). "Some research has reported that RGS1 overexpression in breast cancer facilitates breast cancer progression by regulating Treg cells, while RGS1 overexpression in cardiovascular disease affects disease regression by regulating associated macrophages." (PMID 37735297, 2024). "In multiple cancers, RGS1 has been found to promote T-cell exhaustion, in breast cancer for instance, its upregulation reduced trafficking of anti-tumor lymphocytes to tumors and was associated with shorter survival of patients." (PMID 38918490, 2024). "Previous studies have shown that activation of the INF–STAT1 pathway by some immune cells (such as CTL and Th1 cells) in the breast cancer tumor microenvironment can promote the upregulated transcription of RGS1." (PMID 36225936, 2022). "Recent studies have shown that RGS1 inhibits the transport of Th1 cells and CTLs to tumors, facilitating the formation of 'cold tumors' in breast cancer and impairing antitumor immunity." (PMID 34663417, 2021). "Meanwhile, mouse experiments demonstrated that transfer of tumor-specific CTLs with RGS1 knockdown in combination with PD-L1 could be a promising immunotherapeutic strategy for breast cancer." (PMID 34663417, 2021). "Previous research has shown that the GTPase activator RGS1 in tumor-specific circulating T cells suppresses chemokine receptor signaling, reducing T cell motility and infiltration of CTL and Th1 cells in mouse models, breast cancer, and lung cancer." (PMID 41357574, 2025).
autoimmune disease (8 papers, 2013 to 2025). A disorder resulting from loss of function or tissue destruction of an organ or multiple organs, arising from humoral or cellular immune responses of the individual to their own tissue constituents. "The DE analysis further identified several genes associated with inflammation and autoimmune diseases in the top-20 DEGs such as RGS1, which has been associated with several autoimmune diseases." (PMID 40084238, 2024). "Similar with the locus RGS1, IL12A has been reported with risk of MS and T1D, confirming the shared genetic factors among different autoimmune diseases." (PMID 27043536, 2016). "The capacity of RGS1 to limit the egress of inflammatory and autoimmune cells could encourage the immunopathology of autoimmune disorders." (PMID 32099610, 2019).
multiple myeloma (8 papers, 2021 to 2025). "The aim of the study was to evaluate the expression and the prognostic value of RGS1 and mTOR and their relation to clinical as well as other diagnostic criteria in multiple myeloma." (PMID 37437037, 2023). "MicroRNA-376b-3p can target RGS1 mRNA to inhibit the development of osteosarcoma, and RGS1 expression desensitizes G-protein-coupled receptor signaling and is associated with poor prognosis in multiple myeloma." (PMID 36273177, 2022). "Consolidating KMS-11 as our primary experimental model for investigating the role of p52 in multiple myeloma, we identified several p52-regulated essential genes upregulated in patients, i.e. RGS1 and RHEB, whose expression have been linked to poorer prognosis in MM patients and other cancers." (PMID 38514625, 2024). "In particular, RGS‐1, DUSP2, and CMC1 are associated with immunosuppression and exhaustion as shown in CD8+ T cells of patients with rapidly progressive multiple myeloma." (PMID 39777847, 2025). "RGS1 can impair Treg migration, the class II HLA-DPA1 has been associated with hypoxia in multiple myeloma." (PMID 41208955, 2025). "Hence, it can be postulated that RGS1 is a myeloma driver gene that exerts its oncogenic activity via suppressing p38α mediated antagonism of the GRAP2/JNK-cJun pathway." (PMID 38514625, 2024). "Finally, we functionally validate the pathological impact of these cis-regulatory modules on cell and tumour phenotypes using in vitro and in vivo models, confirming RGS1 as a p52-dependent myeloma driver." (PMID 38514625, 2024). "Further trials for RGS1 and mTOR targeting in multiple myeloma are recommended." (PMID 37437037, 2023). "RGS1 and mTOR were known to play an important role in the pathogenesis of multiple myeloma." (PMID 37437037, 2023). "For instance, RGS1 is highly expressed in multiple myeloma and is a promising target for the treatment of multiple myeloma as a prognostic marker by desensitizing or stimulating receptor activity, thereby altering the GPCR signaling pathway and its downstream activity." (PMID 36120550, 2022).
atherosclerosis (7 papers, 2013 to 2024). A disease characterized by the build-up of fatty material and calcium deposition in the arterial wall resulting in partial or complete occlusion of the arterial lumen. "Here the authors show that Regulator of G-Protein Signaling-1 (RGS1) controls macrophage function in the development of vascular inflammation that underlies atherosclerosis and abdominal aortic aneurysms in mice and humans." (PMID 25782711, 2015). "Upregulation of RGS1 in peripheral blood T lymphocytes decreased their chemotactic response to CXCL12 and CCL19, both implicated in atherosclerosis." (PMID 32443695, 2020). "We investigated the effects of Rgs1 deletion on macrophage recruitment and retention in the artery wall, and elucidate a new requirement for RGS1 in leukocyte accumulation in atherosclerosis and AAA rupture." (PMID 25782711, 2015). "To extend these findings in the mouse atherosclerosis model to human disease, we first evaluated Rgs1 expression in macrophages isolated from human carotid artery plaques obtained at endarterectomy." (PMID 25782711, 2015). "Emerging evidence for a role for RGS1 specifically in atherosclerosis is provided by several human studies that have measured Rgs1 gene expression in vascular disease." (PMID 23690662, 2013). "Thus, RGS1 contributes to the persistence of macrophages in the initial stages of atherosclerosis and promotes aortic aneurysm formation and rupture." (PMID 25782711, 2015). "Among a number of genes already known to play major roles in the development of atherosclerosis such as Ccl2 (MCP-1), Rgs1 was identified as one of the novel candidate genes with higher expression in aortas from older ApoE−/− mice than in aortas from younger ApoE−/− mice." (PMID 25782711, 2015). "For the first time, we provide new evidence for a role for RGS1, a downstream mediator of GPCR signalling, in the recruitment and accumulation of leukocytes to the aorta during vascular inflammation in atherosclerosis, aortic aneurysm formation and aneurysm rupture." (PMID 25782711, 2015). "In our previous study, we examined the T-cell and B-cell phenotype of Rgs1−/−ApoE−/− mice and found no significant alterations, suggesting RGS1 in lymphocytes in the context of atherosclerosis and Ang II induced AAA has a less significant role to that in myeloid cells in vascular inflammation." (PMID 29654907, 2018). "We identified Rgs1 as a novel candidate gene in atherosclerosis and AAA, and tested the hypothesis that RGS1 is a key modulator of chemokine receptor activity, with critical roles in regulating the vascular inflammatory response by affecting macrophage function." (PMID 25782711, 2015). "We examined both the T-cell and B-cell phenotype in of Rgs1−/−ApoE−/− mice and found no significant alterations, suggesting RGS1 in lymphocytes in the context of atherosclerosis and AAA has a less significant role to that in myeloid cells in vascular inflammation." (PMID 25782711, 2015).